ROBO1 (roundabout guidance receptor 1)
Diseases named in the same sentence as ROBO1 in open-access papers (continued):
Sharing a sentence is not in itself a finding about the gene and the disease.
dyslexia (continued). "Thus, the identification of ROBO1 as a susceptibility gene in dyslexia may implicate a key developmental pathway in which slight disturbances may lead to specific reading disability." (PMID 16254601, 2005). "At the molecular level, dyslexia has been associated with genetic variations such as DCDC2, KIAA0319, and ROBO1, which affect neuronal migration and cortical layering." (PMID 40941656, 2025). "They found that there are overlapping expression patterns in human dyslexia-related genes (ROBO1 and KIAA0319, and CNTNAP2 and CMIP) and the expression patterns of these genes in the marmoset brain." (PMID 37760998, 2023). "Furthermore, one dyslexia-associated gene variant of Robo1 causes increased interneuron migration to the cortex, which could be another source for the thickening seen, leading to increased intracortical circuits but no increase in longer cortico-cortical pathways." (PMID 36452335, 2022). "In family pedigrees from Finland, a rare ROBO1 haplotype was identified which dominantly co-segregates with the dyslexia diagnosis." (PMID 34539327, 2021). "Nonetheless, active analyses of the genotype–phenotype association have revealed some possible linkages; for example, GJA5 and cardiac phenotypes, neurexins/neuroligins and synaptic differentiation, or ROBO1 and dyslexia." (PMID 34071723, 2021). "During brain development, two functional copies of ROBO1 are required to have an average reading ability; however, in the event when there is a partial haploinsufficiency for ROBO1, the patient develops dyslexia." (PMID 34674647, 2021). "ROBO1 and ROBO2 genes are mapped at the dyslexia susceptibility loci DYX5, which is located on chromosome 3 (3p12-q13)." (PMID 33425915, 2020). "This same study also showed that ArKO mice have an increase in vertical neuronal density and occasional cortical heterotopia as observed in Robo1 mutant mice and human dyslexia brains, respectively." (PMID 30386297, 2018). "ROBO1, a candidate for dyslexia, is also highly upregulated, whereas, TLE3, a target of FOXP2, is significantly downregulated." (PMID 29922639, 2018). "Several dyslexia susceptibility loci and candidate genes have been identified, with DYX1C1, DCDC2, KIAA0319, and ROBO1 established as the main candidates." (PMID 29045729, 2017). "ROBO1 is a neuronal axon guidance receptor gene involved in brain development and thus an attractive candidate gene for dyslexia." (PMID 20300304, 2008). "Expression of CYP19A1 correlates with expression of dyslexia-risk genes DYX1C1 and ROBO1 raising questions as to whether CYP19A1 acts independently on dyslexia risk." (PMID 36452335, 2022). "Furthermore Roundabout homolog 1 (ROBO1), also implemented in familiar dyslexia, has been identified in the progression of several cancers." (PMID 22375924, 2012). "ROBO1 was identified by the refinement of a breakpoint translocation in one individual with dyslexia and the identification of a rare haplotype co-segregating with dyslexia in a large Finnish family." (PMID 20846247, 2011). "Comparison of genomic and cDNA samples from four dyslexic individuals showed that ROBO1 mRNA was only weakly or not at all transcribed from the allele that segregated with dyslexia, whereas in non-readers' lymphocytes, as well as control brain RNA, biallelic expression was consistently observed." (PMID 16254601, 2005). "Dyslexia is highly heritable and at least four candidate-dyslexia genes have been identified (KIAA0319, DYX1C1, DCDC2 and ROBO1)." (PMID 24871331, 2014). "It is interesting to note that all four of the best characterized candidate-dyslexia genes (KIAA0319, ROBO1, DYX1C1, and DCDC2) interfere with auditory processing." (PMID 24871331, 2014). "Moreover, as reviewed in a recent study, the dyslexia candidate genes including KIAA0319, doublecortin domain containing 2 (DCDC2) and roundabout homolog 1 (ROBO1) are candidate genes involved in speech sound disorder (SSD) as well." (PMID 25178928, 2014).
dyslexia (continued). "Within the three most-replicated dyslexia loci, four candidate genes for dyslexia have been identified: DYX1C1 in DYX1 on chromosome 15q21, DCDC2 and KIAA0319 in DYX2 on chromosome 6p21, and ROBO1 in DYX5 on chromosome 3p12–q12." (PMID 23308072, 2012). "Also supporting a shared biology between SSD and dyslexia, is that other SSD loci co-localize with dyslexia loci, such as DYX5 that includes the axon guidance gene, ROBO1." (PMID 22426781, 2012). "So far, support for ROBO1 has not been reported in additional samples, suggesting its role in the etiology of dyslexia might be restricted to isolated cases." (PMID 20846247, 2011). "While this paper presents conceptual connections between electrophysiological antero-posterior asymmetry and dyslexia-related genes, such as DCDC2, KIAA0319, or ROBO1 this is hypothetical and not a fact due to a lack of genetic or molecular data." (PMID 40941656, 2025).
glioma (24 papers, 2010 to 2025). A benign or malignant brain and spinal cord tumor that arises from glial cells (astrocytes, oligodendrocytes, ependymal cells). "For example, among glioma patients that carry the rs55705857 risk allele, novel variants near ROBO1 were identified that increased the likelihood of having an IDHwt tumor (versus IDHmut tumor) by nine-fold." (PMID 40709013, 2025). "A further interesting example is Roundabout, Axon Guidance Receptor, Homolog 1 (ROBO1) whose expression is implicated in several tumors of the nervous system: a low expression of ROBO1 is related to brain metastasis indicating a poor prognosis, whereas a high expression is common in gliomas." (PMID 28719644, 2017). "Preliminary studies have indicated significant differences in the expression of Slit2 and Robo1 between healthy brain cells and glioma cells." (PMID 40149733, 2025). "By contrast, the percentage of glioma cells expressing Robo1 is higher than that of the control group, and Robo1 is identified as an oncogene." (PMID 40149733, 2025). "This analysis identified novel variants between the roundabout guidance receptor 1 (ROBO1) and receptor 2 (ROBO2) genes that were associated with higher likelihood of being IDHwt (versus IDHmut) among glioma patients that carry the G-allele for rs55705857." (PMID 40709013, 2025). "On the contrary, the percentage of Robo1-expressing glioma cells is higher compared to the control, with Robo1 being perceived as an oncogene." (PMID 39456164, 2024). "In summary, it is evident that Slit2 activity is involved in cell migration and the invasion of glioma cells mediated primarily through Robo1." (PMID 39456164, 2024). "It has been proved that SLIT2/ROBO1 signaling inhibits glioma cell migration and invasion by inactivation of Cdc42-GTP." (PMID 38279111, 2024). "Regarding gliomas, initial studies have shown that Slit2 and Robo1 expression differs between healthy brain cells versus glioma cells." (PMID 39456164, 2024). "An analysis of the TCGA database revealed a significant increase in ROBO1 expression in gliomas compared to normal brain tissues." (PMID 36459288, 2023). "A VM formation assay was conducted using glioma cells transfected with ROBO1 siRNA to clarify the effect of ROBO1 on the development of VM in glioma cells." (PMID 36459288, 2023). "In summary, this study described a microRNA, miR-588, that targets ROBO1 to inhibit invasion, migration and VM formation of glioma." (PMID 36459288, 2023). "Animal experiments revealed that miR-588 reduces the invasive and migratory capabilities of glioma cells by targeting hypoxia-induced roundabout guidance receptor 1 (ROBO1) expression." (PMID 36459288, 2023). "Based on these results, ROBO1 significantly increased the invasion and migration of glioma cells, while ROBO1 knockdown enhanced the ability of miR-588 to inhibit glioma cell invasion and migration." (PMID 36459288, 2023). "To further validate this conclusion that miR-588 exerts its function by targeting ROBO1, we overexpressed ROBO1 in glioma cells transfected with miR-588 mimics." (PMID 36459288, 2023). "ROBO1 knockdown inhibited glioma invasive, migratory, and VM-formation abilities by suppressing the expression of matrix metallopeptidase 2 (MMP2) and matrix metallopeptidase 9 (MMP9)." (PMID 37238655, 2023). "In comparison with the control group, luciferase activity was reduced to approximately 61.3% in cells transfected with miR-588, suggesting that the expression of ROBO1 was directly modulated by miR-588 in glioma cells." (PMID 36459288, 2023). "Roundabout guidance receptor 1 (ROBO1) plays an important role in neurodevelopment and is aberrantly expressed in glioma and pancreatic ductal adenocarcinoma (PDAC)." (PMID 36829563, 2023). "Mechanistically, roundabout guidance receptor 1 (ROBO1) is a direct, functionally relevant target of miR-588 in glioma." (PMID 36459288, 2023).
glioma (continued). "In comparison with the control group, the migration of glioma cells in the scratch assay was significantly reduced after ROBO1 knockdown." (PMID 36459288, 2023). "U87MG glioma cells stably transfected with NC, miR-588 mimics or the miR-588 inhibitor were further transfected with ROBO1 siRNA to verify the effects of ROBO1 on glioma cell invasion, migration and VM." (PMID 36459288, 2023). "Further cell-based experiments revealed a decrease in the invasion, migration and VM-forming abilities of glioma cells after ROBO1 knockdown." (PMID 36459288, 2023). "It has been reported that VMs are probably originated from glioma stem cells; hence, it is probable that ROBO1 abolishes VM formation ability by suppressing stemness." (PMID 33535172, 2021). "An in vitro study revealed an inhibitory role for miR-29a-3p in glioma cell migration and VM formation, and further study confirmed that ROBO1 is a direct target of miR-29a-3p." (PMID 33535172, 2021). "For example, miR-218 suppresses gastric cancer cell proliferation via regulation of angiopoietin-2, and miR-218 inhibits proliferation of glioma cells by targeting ROBO1." (PMID 30157923, 2018). "MiR-203 was found to inhibit glioma cell migration by disrupting the ROBO1/ERK/MMP-9 signaling axis." (PMID 28212562, 2017). "Moreover, this study showed that although both glioma and medulloblastoma tumor cells express Slit2 and Robo1, the recombinant Slit2 protein inhibited only medulloblastoma invasion." (PMID 39456164, 2024). "Furthermore, Robo1 knockdown in glioma cells reversed the chemorepulsive effects of Slit2, confirming that Robo1 serves as the main Slit2 receptor." (PMID 39456164, 2024). "Moreover, both Robo1 and Robo2 expression were detected in tumor cells, suggesting that Slit2 effects in glioma angiogenesis were mediated through these receptors." (PMID 39456164, 2024). "ROBO1 expression gradually increased as the glioma grade increased." (PMID 36459288, 2023). "We concluded that ROBO1 also plays a vital role in the formation of VM structures in glioma cells." (PMID 36459288, 2023). "In glioma, ROBO1 is a direct and functionally important target of miR-588." (PMID 37238655, 2023). "MiR-588 regulated the behaviors of hypoxic glioma cells by targeting ROBO1." (PMID 36459288, 2023). "Normally, knockdown of ROBO1 expression significantly suppresses the migration of glioma cells." (PMID 36459288, 2023). "An analysis of The Cancer Genome Atlas (TCGA) database demonstrated that ROBO1 expression was significantly elevated in glioma tissue in comparison with normal brain tissue, and patients with glioma expressing a high level of ROBO1 experienced significantly shorter survival." (PMID 36459288, 2023). "Moreover, the survival of patients with glioma who expressed ROBO1 at high levels was significantly shortened." (PMID 36459288, 2023). "Based on these results, ROBO1 promotes the development of gliomas." (PMID 36459288, 2023). "ROBO1 knockdown also inhibited the invasion of glioma cells." (PMID 36459288, 2023). "A possible target for glioma prevention and treatment is Slit2/ROBO1 signaling." (PMID 38137332, 2023). "In gliomas, Slit2 and its transmembrane receptor ROBO1 have various distribution patterns; in contrast to ROBO1, which is highly expressed in many grades of gliomas at both the mRNA and protein levels, Slit2 is weakly expressed in pilocytic astrocytoma, fibrillary astrocytoma, and glioblastoma." (PMID 38137332, 2023). "As the results demonstrated, overexpression of miR-588 significantly promoted the invasiveness, migration and VM formation of U87MG glioma cells, while overexpression of ROBO1 could curtail the effect of miR-588 overexpression." (PMID 36459288, 2023). "Based on previous studies, nasopharyngeal cancer progression could be suppressed through Robo1 down-regulation 37, and miR-218 inhibits the migration and invasion of glioma u87 cells through the Robo1 pathway." (PMID 33767589, 2021).
glioma (continued). "It is also well established that miR-203 is down regulated in human glioma and restored expression of miR-203 could negatively regulate migration potential by targeting Robo1/ERK/MMP-9 Signaling cascade." (PMID 27467502, 2016). "Thus, the VM-forming capacity of glioma cells was markedly reduced by ROBO1 knockdown." (PMID 36459288, 2023). "Furthermore, recent studies have suggested that the Slit2/Robo1 signaling might be enlisted for treating glioma because it can inhibit glioma cell migration." (PMID 25299227, 2014). "Over expression of miR-203 drastically suppress Robo1 which in turn suppress ERK phosphorylation and MMP-9 expression thereby repressing glioma cell invasion and migration by disrupting the Robo1/ERK/MMP-9 signaling cascade." (PMID 27467502, 2016). "Roundabout homolog 1 (ROBO1) acts as the direct target of human engineered exosomal miR-29a-3p, and the interaction between miR-29a-3p and ROBO1 plays an important role in glioma migration and vasculogenic mimicry formation." (PMID 39850798, 2024). "ROBO1 knockdown suppressed the expression of matrix metallopeptidase 2 (MMP2) and matrix metallopeptidase 9 (MMP9), thereby inhibiting the invasive, migratory and VM-forming abilities of glioma." (PMID 36459288, 2023). "It was demonstrated that Slit2/ROBO1 signaling prevented glioma cell motility and invasion by inactivating Cdc42-GTP, even though the precise mechanisms behind this tumor-suppressive gene impact of Slit2/ROBO1 remain unknown." (PMID 38137332, 2023). "Furthermore, miR-29a-3p, a tumor suppressor in diverse malignant tumors, was demonstrated to directly target roundabout guidance receptor 1 (ROBO1), thus mitigating vasculogenic mimicry (VM) formation in gliomas." (PMID 35095909, 2021).
pancreatic cancer (20 papers, 2015 to 2025). "Early trials targeting antigens such as HER2 in glioblastoma and ovarian cancer, as well as ROBO-1 in pancreatic cancer, have shown encouraging results, including tumor regression and minimal toxicities." (PMID 40260240, 2025). "Key targets under clinical investigation for pancreatic cancers include PD-L1, an immune checkpoint ligand and ROBO1, a transmembrane receptor from the Ig superfamily." (PMID 40149002, 2025). "In another clinical trial, researchers investigated the novel target, ROBO1, for the treatment of pancreatic cancer (NCT03941457)." (PMID 40149002, 2025). "Research has shown that the expression of Slit2 is downregulated in pancreatic cancer tissue, whereas the expression of Robo1 is upregulated." (PMID 38567163, 2024). "The pre-clinical study showed a significant decrease in tumor size and volume in the anti-ROBO1 CAR-NK-treated orthotopic mouse model of pancreatic cancer." (PMID 37371075, 2023). "Loss-of-function experiments in tumour cells showed that ROBO1 and ROBO3 receptors are involved in pancreatic cancer cell migration and metastasis, and SLIT2 has a role in neural remodelling associated with PDAC11,12." (PMID 30504844, 2018). "Unbiased analysis of the transcriptional network governing the angiogenic switch in human pancreatic cancer identified ROBO1 and SLIT1 as putative proangiogenic genes." (PMID 26674478, 2015). "Knocking out Robo1 can prevent the invasion of pancreatic cancer into the surrounding nerves." (PMID 38567163, 2024). "ROBO1 has been shown to be expressed in various solid tumors, including pancreatic cancer." (PMID 37371075, 2023). "Examinations of the SLIT2 and ROBO1 expression levels in 10 pancreatic cancer cell lines revealed that SLIT2 seldom displays high expression in PDAC cell lines, especially in liver metastasis-derived CAPAN-1 and cFPAC-1 cells with relatively high ROBO1 expression." (PMID 36792623, 2023). "Knocking out Robo1 can enhance the invasion and metastasis of pancreatic tumors." (PMID 32670371, 2020). "Finally, miR-218 was shown to inhibit tumor cell invasion and migration by regulating ROBO1 in pancreatic cancer." (PMID 31310241, 2019). "On the other hand, Robo1 is not only found in the myofibroblasts but also frequently found in pancreatic tumour epithelium where, as referred above, it might play a distinct role in migration and invasion." (PMID 30504844, 2018). "Low Robo1 expression levels may thus contribute to gemcitabine resistance in pancreatic cancer." (PMID 32670371, 2020). "Three studies focusing on targeting ROBO1 by BiCAR-NK/T cells (ROBO1-CAR-NK/T cells) are ongoing in China and are intended to investigate the effects of CAR-NK cells on pancreatic cancer (NCT03941457), solid (NCT03940820) and malignant (NCT03931720) tumors." (PMID 34923966, 2021). "This included elements of the Hedgehog signaling pathway (SHH, GAS1), semaphorin signaling (SEMA3A, PLXNA1, PLXNB2, PLXND1, PLXNA2, FARP1, FARP2) and also axon guidance pathways (ROBO1, SLIT1, SLIT3 and SLITRK2), all notable for their involvement in pancreatic cancer progression and metastasis." (PMID 36429078, 2022). "Considered that ROBO1 plays a key role in angiogenesis, and we hypothesized that SRGAP2 and ROBO1 coregulate angiogenesis in pancreatic cancer." (PMID 36277474, 2022).